NAMPT (nicotinamide phosphoribosyltransferase)
Diseases named in the same sentence as NAMPT in open-access papers (continued):
Sharing a sentence is not in itself a finding about the gene and the disease.
melanoma (continued). "Altogether, we conclude that IFNγ-inducible NAMPT is an important player in melanoma cell growth." (PMID 36900204, 2023). "Our data elucidates a mechanism by which IFNγ upregulates NAMPT in both human and mouse melanoma cells by inducing the signal transducer and activator of transcription 1 (STAT1) transactivation via a conserved enhancer that we recently identified in tumor-associated macrophages." (PMID 36900204, 2023). "In this study, we found that IFNγ induces NAMPT in both human and mouse melanoma cells." (PMID 36900204, 2023). "After observing the IFN induction of NAMPT expression in melanoma cells, we investigated whether IFNγ-inducible NAMPT promoted proliferation in vitro." (PMID 36900204, 2023). "Previous literature implicates NAMPT in melanoma proliferation." (PMID 36900204, 2023). "In all cases, IFNγ significantly induced NAMPT expression in mouse and human melanoma cells." (PMID 36900204, 2023). "NAMPT overexpression confers resistance to specific drugs (chemotherapeutic agents and selective kinase inhibitors) in several tumor models, including glioma, colon cancer, sarcoma, breast cancer, and melanoma, as detailed in the next paragraph." (PMID 36077374, 2022). "Moreover, in vitro studies showed the increased secretion of visfatin/NAMPT from inter alia, melanoma cells, or human pancreatic adenocarcinoma cells." (PMID 36233428, 2022). "Moreover, the RT-PCR analysis in our clinical samples demonstrated that EBI3, ERAP1, and NAMPT mRNA expression levels were significantly upregulated in melanoma tissues compared to normal tissues." (PMID 35326741, 2022). "Furthermore, a proteomic study reported an upregulation of NAMPT in melanoma cells resistant to MAPKi along with a mesenchymal-like phenotype." (PMID 35406721, 2022). "Since both the activation of mTOR and NAD metabolism via NAMPT are involved in the therapeutic resistance of melanoma to BRAFi/MEKi, an outstanding question is whether in this context these two these two key molecular pathways are functionally interconnected." (PMID 36077374, 2022). "NAMPT was highly upregulated in glioma, lung cancer, head and neck cancer, and melanoma." (PMID 35565188, 2022). "Furthermore, NAMPT expression in the tumor was increased in people who died from melanoma and in the advanced stages of this cancer." (PMID 34068679, 2021). "NAMPT could become a predictive marker of anti-PD-L1 therapy, and this would be an important finding if confirmed also in melanoma, thinking to combination therapy with NAMPT inhibitor and/or blocking antibody with targeted and immunotherapy." (PMID 34073463, 2021). "Furthermore, TCGA melanoma samples show a significant positive correlation between NAMPT and IFNG expression, and more broadly between NAMPT levels relative to the GSEA Hallmark IFNγ response gene set." (PMID 33976173, 2021). "Analyzing specific genes involved in phenotypic plasticity, the TCGA dataset confirmed the direct and significant correlation between expression levels of molecules connected to EMT (ZEB1) and stemness (YAP1, ABCC4) molecules, as well as NAMPT in melanoma patients." (PMID 33419372, 2020). "In fact, in vitro studies revealed that melanoma treatment with NAMPT inhibitors (NAMPTi) reduces NAD and ATP, depolarizes the inner mitochondrial membrane with loss of mitochondrial membrane potential, triggers ROS release, halts cells in the G2/M phase and induces apoptosis." (PMID 32528879, 2020). "Overall, our results support the hypothesis of a driving role of NAMPT in melanoma progression and the clinical use of NAMPT inhibitors in combination with BRAFi/MEKi to avoid onset resistance." (PMID 33419372, 2020). "Herein, we provided complete and definitive evidence that NAMPT may be considered as a main driving force for drug resistance and melanoma progression and aggressiveness." (PMID 33419372, 2020). "This makes NAMPT an actionable target for melanoma treatment." (PMID 32528879, 2020).
melanoma (continued). "In addition, induced expression of NAMPT was able to render melanoma cells resistant to BRAF inhibitors while BRAF inhibition in sensitive cells resulted in transcriptional downregulation of NAMPT." (PMID 32010616, 2019). "Additionally, melanomas have higher levels of NAMPT; therefore, we investigated whether IFNs induce NAMPT in melanoma cells." (PMID 36900204, 2023). "The treatment of melanoma cells with the NAMPT inhibitor FK866 caused the production of ROS, blocked cancer cells at G2/M phase, leading to cell apoptosis, and improved mouse survival in a xenograft model, demonstrating that NAMPT is a therapeutic target in metastatic melanoma with BRAF mutation." (PMID 35565188, 2022). "Finally, elevated NAMPT expression correlates with IFNγ responses and melanoma patient survival." (PMID 33976173, 2021). "Overall, the results of this work revealed that NAMPT over-expression is a key event in mediating drug resistance and in increasing aggressive features of melanomas opening to the hypothesis of a direct oncogenic role for this enzyme in melanoma tumorigenesis." (PMID 33419372, 2020). "NAMPT synergizes with IFN-γ to regulate PDL1 expression, leading to immune evasion by melanoma cells." (PMID 40108693, 2025). "Specifically, NAMPT is the rate-limiting enzyme of the NAD+ salvage pathway in mammals and increases in its expression/activity play key roles in melanoma therapeutic resistance to BRAF/MEKi." (PMID 38755661, 2024). "The immunohistochemical results of the Human Protein Atlas dataset demonstrated that four hub genes (A2M, NAMPT, LIF, and ERAP1) are overexpressed in melanoma tissues." (PMID 35326741, 2022). "On this basis, it is concluded that the combination of NAMPT and BRAF inhibitors has the potential to be a new therapy for BRAFi-sensitive patients with melanoma." (PMID 34068679, 2021). "NAMPT that is involved in the conversion of nicotinamide to NAD, has been found upregulated in tissue biopsies from melanoma patients after the development of BRAFi resistance." (PMID 32528879, 2020). "Consistently, in BRAFi-resistant melanomas, NAD metabolism is increased through the selective up-regulation of the nicotinamide pathway via NAMPT activity." (PMID 33419372, 2020). "As recently reviewed, nicotinamide phosphoribosyltransferase (NAMPT) plays a critical role in NAD+ synthesis and energy control and its role in melanoma, mediated by BRAF and Sirtuins, is being recognized with increasing evidence." (PMID 33028392, 2020). "Decrease in EMT markers (E-cadherin, YKL-40, N-cadherin, SNAI1) were seen with simultaneously decline in melanoma cells (BRAF, NAMPT) and stem cells (CD133, ABCB5) markers." (PMID 31126298, 2019). "In clinical mouse trials, increased IFN-γ activity induces NAMPT expression within the melanoma cells by enhancing the nicotinamide adenine dinucleotide (NAD+) salvage pathway, allowing greater energy and metabolic activity that enhances melanoma tumor growth." (PMID 40872475, 2025). "In BRAFV600E melanoma cells, the inhibition of STAT5 decreases NAD+ levels via NAMPT inhibition, while in cervical cancer cell line SiHa, STAT5 probably regulates the expression of NAMPT because its inhibition reduces NAD+ levels." (PMID 38999946, 2024). "NAMPT orchestrates an effective antitumor immune response in macrophages within the TME, whereas selectively interfering with NAMPT in melanoma cells may improve the efficacy of IFN-based immunotherapies." (PMID 36900204, 2023).
melanoma (continued). "Recently, activation of nicotinamide adenine dinucleotide (NAD) metabolism and, in particular, of its rate-limiting enzyme nicotinamide phosphoribosyltransferase (NAMPT) have been identified as key drivers of targeted therapy resistance and melanoma progression." (PMID 36077374, 2022). "The results demonstrated that EBI3, ERAP1, and NAMPT mRNA levels were upregulated in melanoma tissues, while A2M and LIF were not insignificant." (PMID 35326741, 2022). "On the other hand, in another study, enzymatic inhibition of NAMPT did not result in lower melanoma cell viability." (PMID 34068679, 2021). "Interestingly, the inhibition of BRAF in melanoma cell lines has been reported to achieve high levels of NAD, which were activated by the overexpression of nicotinamide phosphoribosyltransferase (NAMPT), the most important NAD biosynthetic enzyme." (PMID 32858528, 2020).
colorectal cancer (33 papers, 2011 to 2025). A primary or metastatic malignant neoplasm that affects the colon or rectum. "Previous research reported that nicotinamide phosphoribosyltransferase-driven tumor-associated macrophage M2 polarization results in an immunosuppressive microenvironment in colorectal cancer." (PMID 40427533, 2025). "Previous studies have shown that NAMPT plays a crucial role in promoting the progression of colorectal cancer and is associated with patient prognosis." (PMID 40463392, 2025). "NAMPT was discovered to be overexpressed in colorectal cancer, and its expression was associated with inferior overall survival." (PMID 35565188, 2022). "Second, in some other cancers, such as colorectal cancer, NAMPT and NAPRT high expression are seen to be associated with poor prognosis for the patient." (PMID 36249025, 2022). "These molecular mechanisms imply that inhibition of NAMPT enzymatic activity or expression in tumor microenvironmental components is possibly a viable therapeutic strategy for colorectal cancer patients." (PMID 38308188, 2024). "For instance, inhibiting nicotinamide phosphoribosyltransferase (NAMPT) has been shown to suppress colorectal cancer cell proliferation by increasing AXIN1 expression." (PMID 38291457, 2024). "NAMPT has been reported upregulated in different cancers like, colorectal cancer prostate, breast and gastric cancers and this dysregulation is linked to promote tumor glycolysis, metastasis, invasion, proliferation, survival, and chemotherapy resistance." (PMID 36809279, 2023). "Similar results were reported in another study showing that overexpressed NAMPT in colorectal cancer tissues was correlated with a poor survival rate." (PMID 35565188, 2022). "On the other hand, in patients diagnosed with colorectal cancer and gastric cancer determined by array, those with high NAMPT expression levels are correlated with better clinical outcomes." (PMID 35565188, 2022). "An analysis of public data extracted from the Oncomine and PrognoScan databases indicated the overexpression of NAMPT in human colorectal cancer." (PMID 35565188, 2022). "In a colorectal cancer study, NAMPT knockdown led to reduced cell proliferation via impaired Wnt/β-catenin signaling, and Axin-mediated β-catenin degradation was detected." (PMID 35565188, 2022). "Our study indicated that the inhibition of NAMPT decreased proliferation capacity of colorectal cancer cells both in vitro and in vivo." (PMID 32005247, 2020). "Transwell migration and invasion assays were conducted to assess the role of NAMPT in cell migration and invasion abilities of colorectal cancer cells." (PMID 32005247, 2020). "Real-time PCR, immunohistochemistry, western blotting, and analyses of datasets from Oncomine and Gene Expression Omnibus were conducted to assess the expression of NAMPT at the mRNA and protein levels in colorectal cancer." (PMID 32005247, 2020). "Knockdown of NAMPT was performed to assess the role of NAMPT in colorectal cancer cell proliferation and tumorigenesis both in vitro and in vivo." (PMID 32005247, 2020). "Overexpression of NAMPT was used to evaluate impact of NAMPT on colorectal cancer cell proliferation in vitro." (PMID 32005247, 2020). "In a previous study, it was found that FK866, a small molecule inhibitor of nicotinamide phosphoribosyltransferase (NAMPT), caused significant metabolic changes in purine metabolism in ovarian cancer and colorectal cancer cells." (PMID 28420117, 2017). "S100 calcium-binding protein A9, annexin A3, nicotinamide phosphoribosyltransferase, carboxylesterase 2 and calcium activated chloride channel A1 were probably potential biomarkers of colorectal cancer." (PMID 27661117, 2016).
colorectal cancer (continued). "To assess NAPRT and NAMPT expression in tumors, we studied a set of cell lines, which included renal, thyroid, cervix, lung, gastric and colorectal carcinomas, uveal melanoma, and leukemia, by RT-PCR and western blot." (PMID 26675378, 2016). "In colorectal cancer, visfatin-induced stemness was shown to be related to stem cell signaling transduction and radiotherapy resistance, with a positive correlation being found between stemness-related marker expression and NAMPT expression." (PMID 36830834, 2023). "Furthermore, higher NAMPT levels were detected in colorectal cancer tissues than in paired normal tissues, especially in cancer patients with stage I and II disease." (PMID 35565188, 2022). "In a clinical study of 261 colorectal cancer patients, high expression of NAMPT determined by immunohistochemical staining appeared to be correlated with advanced TNM stage, vascular invasion, invasion depth, and unfavorable overall survival and disease-free survival time." (PMID 35565188, 2022). "It is unknown whether NAMPT regulates colorectal cancer proliferation through Wnt/β-catenin signaling pathway." (PMID 32005247, 2020). "In addition, we showed that colorectal cancer tissues harbored significantly higher levels of NAMPT than the levels harbored by paired normal tissues, especially in colorectal cancer stages I and II." (PMID 32005247, 2020). "Our findings reveal that NAMPT plays an important role in colorectal cancer proliferation via Wnt/β-catenin pathway, which could have vital implications for the diagnosis, prognosis and treatment of colorectal cancer." (PMID 32005247, 2020). "Here, we assessed the role of NAMPT in the proliferation of colorectal cancer." (PMID 32005247, 2020). "NAMPT inhibition induced β-catenin degradation by increasing Axin expression levels; this resulted in the inhibition of Wnt/β-catenin signaling and cell proliferation in colorectal cancer." (PMID 32005247, 2020). "Nuclear factor I B promotes colorectal cancer cell proliferation in vitro and growth in vivo by increasing intracellular NAD+ levels through downregulation of the NAMPT-targeting micro-RNA, miR-182-5p." (PMID 37491379, 2023). "Blood exosomes from 58 colorectal cancer (CRC) patients and 28 healthy controls were collected and NAMPT-Antisense (NAMPT-AS) and Nicotinamide phosphoribosyl-transferase (NAMPT) mRNA were quantified by RT-qPCR, showing that they were upregulated in patients with CRC." (PMID 40075875, 2025). "Taken together, our results indicate that NAMPT inhibition does not influence invasion and migration abilities of colorectal cancer cells in vitro." (PMID 32005247, 2020). "Increased levels of c-Myc in the human colorectal cancer cells positively correlate with high SIRT1 protein expression; furthermore, conditional activation of c-Myc increases levels of SIRT1 protein, NAD+, and NAMPT mRNA in several cell types." (PMID 31689236, 2019).
pancreatic cancer (30 papers, 2014 to 2025). "Inhibition of NAMPT has been reported to sensitize pancreatic cancer cells to gemcitabine chemotherapy by decreasing NAD levels and suppressing glycolytic activity." (PMID 40805270, 2025). "Several studies have highlighted the upregulated expression of NAMPT in various cancers, including colorectal, breast, ovarian, endometrial, prostate, and pancreatic cancers, with higher NAMPT expression often being correlated with poorer survival outcomes." (PMID 39272943, 2024). "In this study, analysis of TCGA database also showed that various tumors, including pancreatic cancers, have frequent gene amplification of NAMPT and NMNAT2." (PMID 38625917, 2024). "NAMPT inhibition suppressed mTOR signaling in multiple myeloma cells, hepatocarcinoma cells, and pancreatic cancer cells." (PMID 38116009, 2023). "Being overexpressed in several types of malignant tumors, including pancreatic cancer, NAMPT was considered a very promising therapeutic target." (PMID 37242714, 2023). "The nicotinamide phosphoribosyltransferase (NAMPT) is considered a very promising therapeutic target because it is overexpressed in pancreatic cancer." (PMID 37242714, 2023). "The inhibition of NAMPT impairs pancreatic cancer growth in vitro and in vivo, and this impairment was rescued by supplementation of nicotinamide mononucleotides." (PMID 36144235, 2022). "Together, these results show that metformin and the NAMPT inhibitor cooperate to inhibit growth and to induce oxidative stress and cell death of pancreatic cancer cell lines in vitro." (PMID 36428689, 2022). "This is consistent with previously published data on the proliferative effects of NAMPT expression in pancreatic cancer cells in vitro and in vivo." (PMID 30856230, 2019). "Using 3 different human pancreatic cancer cell lines (BxPC3, MiaPaCa2 and Panc1), a single band of NAMPT of the correct molecular weight was obtained on immunoblot analysis, showing the specificity of the monoclonal antibody used in this study." (PMID 30856230, 2019). "We have unpublished preliminary data showing elevated serum levels of NAMPT in obese and/or diabetic patients with pancreatic tumors." (PMID 30856230, 2019). "Inhibition of NAD synthase via NAMPT pathway blocks the cell growth and survival of pancreatic tumor both in vitro and in vivo." (PMID 31225458, 2018). "NAMPT inhibitors have shown preclinical efficacy in a plethora of cancer models, including pancreatic cancer." (PMID 29156703, 2017). "The main aims of this study were to evaluate the STF efficacy as a treatment for pancreatic cancer, as well as to compare its efficacy with the first generation NAMPT inhibitor, FK866." (PMID 29156703, 2017). "It has been shown that pancreatic cancer cells mainly rely on the savage pathway of NAD synthesis where NAMPT is the rate committing enzyme found to be overexpressed in many cancers and to correlate with their development." (PMID 28476035, 2017). "Our previous study showed the importance of NAMPT in maintaining NAD levels in pancreatic ductal adenocarcinoma cells (PDAC), and that the NAMPT inhibitor FK866 decreased pancreatic cancer growth." (PMID 29156703, 2017). "NAMPT overexpression has been recently found in colorectal, breast, prostatic, gastric, esophageal, and pancreatic cancers." (PMID 25946974, 2015). "This study also aimed to investigate if MAP17-expressing cells have a higher NAD pool, and if the depletion of this pool by Nicotinamide phosphoribosyltransferase (NAMPT) inhibitors could sensitize cells to classic chemotherapy in pancreatic tumor xenografts." (PMID 40805270, 2025). "Pancreatic tumor patients could be stratified based on MAP17 expression to receive a combination treatment of current agents with NAMPT inhibitors, which seems to sensitize cells to traditional treatments only in tumors with high MAP17 expression." (PMID 40805270, 2025).